ID1 (inhibitor of DNA binding 1)
Diseases named in the same sentence as ID1 in open-access papers (continued):
Sharing a sentence is not in itself a finding about the gene and the disease.
breast carcinoma (continued). "In breast cancer, Id1 and Id3 are expressed predominately in triple negative tumors (estrogen -, progesterone -, and Her2Neu-)." (PMID 23593444, 2013). "The E47/Id1 interaction and inability of Id1 to reactivate the E-cadherin promoter was further confirmed in E47-expressing basal-like breast carcinoma and melanoma cells." (PMID 23555842, 2013). "Here, we show that E47 interacts with Id1 in E47 overexpressing MDCK cells that underwent a full EMT as well as in mesenchymal breast carcinoma and melanoma cell lines." (PMID 23555842, 2013). "ID1 expression also harbor prognostic information in breast cancer as ID1 expression increase with tumor grade and is an independent prognostic marker." (PMID 23029547, 2012). "Observations have suggested heterogeneity in Id1 and Id3 possibly due to high degree of sequence similarity: both Id1 and Id3 are required for neurogenesis, angiogenesis, and vascularization of tumor xenografts and involved in breast cancer lung metastasis." (PMID 23342268, 2012). "It has previously been shown that silencing cyclin D1 increases the migratory capacity of MDA-MB-231 breast cancer cells with concomitant increase in 'inhibitor of differentiation 1' (ID1) gene expression." (PMID 21955753, 2011). "In this study, we demonstrate that silencing Id1 prevents the cyclin D1 mediated increase in MDA-MB-231 breast cancer cell migration." (PMID 21955753, 2011). "Given the role of Id1 in cell invasion and metastasis, it represents a strong candidate for driving breast cancer cell migration following cyclin D1 silencing." (PMID 21955753, 2011). "To directly address this, we examined TGF-beta (a known inducer of Id1) gene expression in a range of breast cancer cell lines and noted high levels in MDA-MB-231 cells relative to ZR75-1 cells." (PMID 21955753, 2011). "This suggests that Id1 expression is activated during mammary neoplasia and that the prognostic significance of Id1 expression in breast cancer cohorts should be re-evaluated using this new monoclonal antibody, which we are currently pursuing." (PMID 20689821, 2010). "The Inhibitor of Differentiation 1 (Id1) protein has well documented roles in the control of mammary epithelial differentiation and proliferation in vitro and breast cancer progression in vivo." (PMID 20689821, 2010). "While we did not readily detect Id1 in the normal mammary epithelium, we did detect Id1 expression in a mouse mammary cancer model, and have similarly detected Id1 in human breast cancer cell lines and clinical cases (AS, unpublished data)." (PMID 20689821, 2010). "Id1 is also reportedly upregulated in breast cancer, with high expression correlating with poorer patient outcome." (PMID 20689821, 2010). "Id1 expression has previously been reported to correlate with poor prognosis in breast cancer, however that study used the polyclonal antibody that we report here to be non-specific and insensitive in mouse tissues." (PMID 20689821, 2010). "Separately, we reported that the presence of E6/E7 of HPV type 16 is correlated with Id-1 overexpression in human invasive and metastatic breast cancer tissues in Canadian women." (PMID 18648363, 2008). "In breast cancer patients, enhanced Id-1 expression is correlated with more aggressive behaviour as well as much shorter overall survival." (PMID 18648363, 2008). "Overexpression of Id-1 promotes mammary epithelial cell invasion, and reduced expression of Id-1 in metastatic breast cancer cells leads to a decrease in invasiveness in vitro." (PMID 18000500, 2007). "A study of breast cancer suggested that ID1 can control the malignant progression of breast cancer cells, particularly when mediated by sex steroid hormones." (PMID 16189525, 2005). "There are a number of possible explanations for this discrepancy concerning the Id-1 role in the prognoses between pancreatic cancer and other human cancers, such as cervical and breast cancers." (PMID 15026801, 2004).
breast carcinoma (continued). "Additionally, Id1 knockdown in 4T1.13 murine breast cancer cells demonstrated reduced tumour growth and metastasis in vivo." (PMID 40116596, 2025). "To better understand how ID1 might relate to biological processes during breast cancer progression, we performed differential gene expression (DGE) analysis between primary tumours versus combined liver and lung samples using degust." (PMID 40116596, 2025). "The systemic delivery of an antisense molecule to ID1, peptide conjugate antisense oligonucleotide (ID1-PCAO), can effectively reduce ID1 protein levels in tumor endothelium to inhibit primary tumor growth and metastatic spread of lung cancer and breast cancer." (PMID 41146039, 2025). "Cannabidiol also inhibits the invasiveness of aggressive MDA‐MB‐231 and MDA‐MB‐436 breast cancer cell lines by downregulating inhibitor of DNA binding 1 (ID‐1), a transcriptional regulator, which stimulates the metastasis in a mouse model of advanced breast cancer with lung metastases." (PMID 39503169, 2024). "Furthermore, a direct proportional expression between MYC and ID1/3 was observed, further strengthening the existence of a MYC, ZNF148, and ID1/3 regulatory axis in controlling the stemness in breast cancer." (PMID 36207293, 2022). "Given the MYC-ZNF148-ID1/3 regulatory axis found in this study, ZNF148 may be involved in the TGF-β downstream pathways, mediating the repression of ID1/3 genes, thus reducing the cancer stem cell properties in breast cancer." (PMID 36207293, 2022). "Breast cancer promotion by Id-1 was shown to be mediated by the Wnt/c-myc pathway as pharmacological inhibition of Wnt/c-myc blocked tumorsphere formation in Id-1 overexpressing MCF7 cells and acceleration of tumorigenesis was accompanied by increased c-myc expression." (PMID 34736527, 2021). "The antimetastatic effect on breast cancer cells demonstrated for CBD in a mouse model was shown in a later work to be reversible by ectopic expression of Id-1 in breast cancer cells, so that the antimetastatic action of CBD can also be directly linked to Id-1 downregulation." (PMID 34830856, 2021). "Evidence to date shows ID1 expression in many tumor types, including breast cancer." (PMID 33514024, 2021). "Study indicated that Id1 promotes breast cancer metastasis by S100A9 regulation." (PMID 32410828, 2020). "Targeting Id1 expression in breast cancer cells reduces breast cancer metastasis in animal models." (PMID 32410828, 2020). "In breast cancer, Naa10p inhibited metastasis through binding to the transcription factor, signal transducer and activator of transcription 5a (STAT5a), and decreasing STAT5a-mediated ID1 expression." (PMID 32719332, 2020). "Notably, gene expression of ID1 promotes formation of lung metastases by itself in animal models and is highly expressed in samples from breast cancer patients with lung metastases." (PMID 31330946, 2019). "Indeed, the DNA-binding protein inhibitor ID-1 is a protein that is encoded by the ID1 gene and its activation promotes breast cancer dissemination by modulating S100A9 expression." (PMID 31330946, 2019). "Though decreased CCND1 activity may block proliferation, low CCND1 has been shown to correlate with high ID1 levels, as seen in the 20 mm region, which may promote more aggressive breast cancer tumor phenotype and metastasis." (PMID 30325954, 2018). "More significantly, we have demonstrated that E6/E7 onco-proteins of HPV type 16 bind and active Id-1 promotor in human breast cancer cells; in parallel, we reported that Id-1 is the main regulator of cell invasion and metastasis induced by E6/E7 onco-proteins in these cancer cells." (PMID 30035100, 2018). "ID1 was also found in a lung metastatic gene signature of breast cancer." (PMID 29376829, 2018).
breast carcinoma (continued). "Interestingly, Twist1 silencing in breast cancer cells can be mediated by ID1 (inhibitor of differentiation 1) promoting a stem‐like phenotype while maintaining epithelial properties at distant sites." (PMID 28590039, 2017). "In breast cancer Id1 plays a crucial role in phenotype switching during lung metastasis." (PMID 28122577, 2017). "The anti-invasion role of KLF17 has been reported to regulate Id1 expression in breast cancer." (PMID 28454121, 2017). "Id1 has been reported as a negatively regulated gene by KLF17 in breast cancer." (PMID 28454121, 2017). "This complex context-dependent function of ID1 allows breast cancer cells to retain their EMT-cancer stem cell-like mesenchymal phenotype during tumor initiation and metastatic dissemination, and to re-acquire their epithelial character necessary for lung colonization." (PMID 28611292, 2017). "Accordingly, overexpressed Id1 may lead to oncogenic transformation of mammary stem cells, which promotes cancer stem cell activity in breast cancer cells." (PMID 28122577, 2017). "This correlates with the inhibition of Id1 in mouse and human breast cancer cell lines." (PMID 28122577, 2017). "Cooperating with oncogenic Ras, ID1 triggers metastatic transformation of mammary carcinoma." (PMID 26662959, 2016). "Taken together, DJ-1 could promote the invasion of breast cancer cells via regulating the KLF17/ID1 pathway." (PMID 26662959, 2016). "Consistent with our previous finding that Id1 activates the Wnt/β-catenin/TCF pathway in human breast cancer, treatment with FH535, a small-molecule inhibitor of Wnt/β-catenin, repressed Id1-mediated c-Myc expression in MECs from MMTV-Id1 mice as confirmed by western blot and RT-PCR analysis." (PMID 25938540, 2015). "Together, these findings could suggest that Id1 increases deregulation of mammary basal stem cells, thereby inducing basal-like breast cancer." (PMID 25938540, 2015). "Because Id1 contributed to the development of ductal hyperplasia and mammary tumors, we investigated whether Id1 could influence CSC activity in human breast cancer cell lines." (PMID 25938540, 2015). "A previous study revealed that COX-2-driven PGE2 induces expression of Id1 in breast cancer cells." (PMID 24659686, 2014). "This factor has been shown to be regulated by COX-2 in breast carcinoma cells and recent studies suggest that Id1 may also be involved in the genesis/progression of gliomas." (PMID 24659686, 2014). "Moreover, functional studies have shown that Id1 and Id3 are required for both, tumor initiation and during metastatic colonization of the lung microenvironment by breast cancer cells." (PMID 23311395, 2013). "Interestingly, Id1 expression in breast cancer cells has been correlated with poor prognosis and lung metastasis." (PMID 23555842, 2013). "At present, very little is known about the expression of E47 and IDs and their correlation with specific subtypes of human breast carcinomas, although ID1 expression has been correlated with poor prognosis, metaplastic tumours and lung metastasis in breast carcinomas." (PMID 23555842, 2013). "High-risk HPV infection was associated with upregulated expression of the Id-1 transcription factor (a family of helix–loop–helix transcription factors) in aggressive breast cancer tissues, and suggested that the virus can induce cell invasion and metastasis via Id-1." (PMID 24138789, 2013). "Id1 has previously been implicated with EMT both directly, through suppression of E-cadherin and zonula occludins-1 (ZO-1), in human kidney cells and indirectly, through loss of Krueppel-like factor 17 (KLF17) in breast cancer cells." (PMID 21955753, 2011).
breast carcinoma (continued). "As a role for Id1 in breast cancer cell metastasis and aggressiveness has previously been suggested, it was logical to examine whether it was also responsible for the cyclin D1 induced increase in cell migration." (PMID 21955753, 2011). "Intermediate expression of ID1 could be detected in the remaining leukemic cell lines and in two breast cancer cell lines, T47-D and MDA-MB453, whereas MCF-7 and MDA-MB468 only showed very low ID1 expression." (PMID 20070914, 2010). "Moreover, we demonstrated that E6/E7 onco-proteins of HPV type 16 convert non-invasive breast cancer cells to an invasive phenotype; this is accompanied by an overexpression of Id-1, which regulates cell invasion and metastasis of human breast cancer cells." (PMID 18648363, 2008). "Moreover, the ectopic expression of Id-1 increases the proliferation, migration, invasion and metastasis of breast cancer cells." (PMID 15026801, 2004). "The Inhibitor of Differentiation Protein 1 (Id1) and its closely related family member Inhibitor of Differentiation 3 (Id3) (collectively termed Id) are expressed by a diversity of stem cells and are required for metastatic dissemination in experimental models of breast cancer." (PMID 32766238, 2020). "Also the sex hormone estradiol positively affects Id1 gene expression in human breast cancer cells, which, however, may be counteracted by progesterone." (PMID 28122577, 2017). "Notably, our finding that Id1-induced ductal hyperplasia and breast tumors exclusively express basal markers could suggest the generation of basal-like breast cancer by Id1." (PMID 25938540, 2015). "Furthermore, in Id1-overexpressing MCF7 luminal type breast cancer cells, the CD44+/CD24−/ESA+ breast CSC population was enriched, whereas short hairpin RNAs (shRNAs)-mediated Id1 knockdown in MDA-MB-231 basal-like type breast cancer cells reduced the size of this population." (PMID 25938540, 2015). "In addition, COX-2 has been shown to regulate Id1 expression in a breast carcinoma line." (PMID 24659686, 2014). "Moreover, we have confirmed a relationship between cyclin D1, Id1 and EMT in primary breast cancer, supporting our in vitro findings that low cyclin D1 expression can be linked to aggressive features in subgroups of breast cancer." (PMID 21955753, 2011). "Furthermore, since Id1 is expressed by breast cancers we wanted to test whether Id1 expression can initiate hyperplastic or neoplastic change in the mammary gland." (PMID 20689821, 2010). "Both ID1 (an MMP2 inhibitor) and MMP2 exhibited a significant decrease in expression in breast cancer cases within the Control group, coupled with greater expression in fibroadenoma samples." (PMID 40806434, 2025). "As first described in breast cancer, TGF-b has been shown to increase the CD44high cell population through Id1." (PMID 41303422, 2025). "In breast cancer studies, bidirectional regulation between autocrine IGF2 and inhibitor of DNA-binding 1 (Id1) promotes tumor stemness." (PMID 38887298, 2024). "In breast cancer, the TGF-β induced upregulation of ID1 promotes mesenchymal-epithelial transition, playing a crucial role in the colonization stage of metastasis." (PMID 38658527, 2024). "For instance, ID1 promoted lung cancer growth by activating CDK4/cyclin D1 and breast cancer metastasis through S100A9 regulation." (PMID 37759448, 2023). "In breast cancer, glioblastoma and salivary gland cancer cells, a CBD-mediated downregulation of Id-1, an inhibitor of basic helix-loop-helix transcription factors, has been reported as the cause of the anti-invasive effect of this compound." (PMID 35277658, 2022).
breast carcinoma (continued). "ID1 and ID3 proteins are functionally redundant and have been shown to promote breast cancer cell self-renewal, tumor cell dissemination, and metastatic colonization of the lung and tumor re-initiation." (PMID 36207293, 2022). "As a tumor suppressor, TGF-β reduces the breast cancer stem cell population, and cell proliferation via MYC, ID1, and ID3 genes." (PMID 36207293, 2022). "The dysregulation of LKB1-SIK-CREB axis induces the expression of the inhibitor of DNA binding 1 (ID1), an oncogene already studied and demonstrated to be essential for lung colonization by breast cancer." (PMID 35646638, 2022). "In breast cancer biopsies, ID4 and ID1 are overexpressed in a subset of samples that predominantly presented more aggressive phenotypes and shorter overall and disease-free survival." (PMID 33514024, 2021). "We confirmed that the overexpression of ID1 and ID4 correlated with more aggressive phenotypes and poor survival in breast cancer patients’ samples." (PMID 33514024, 2021). "A study by McAllister and colleagues investigated CBD treatment of a murine model of metastatic breast cancer and found CBD inhibited Id-1 gene expression in the primary tumour and lung metastasis in vivo through modulation of the ERK and ROS pathways." (PMID 34259916, 2021). "Real-time quantitative PCR validation of RNA-seq data was done for IDH2, ID1, KRT80, and CALCR genes both in circNFATC3 silenced MDA-MB-231 breast cancer cells and SK-OV-3 ovarian cancer cells." (PMID 33816459, 2021). "To further characterize the effects of AGX51 in cancer cells, we treated the 4T1 murine mammary cancer cell line with increasing concentrations of AGX51 (0–80 μM) for 24 h and observed a significant decrease in ID1 protein levels starting at 40 μM." (PMID 34031428, 2021). "The correlation between ID1 and KIF11 gene expression and relapse free-survival of breast cancer patients was analyzed by the KM Plotter database." (PMID 32911668, 2020). "A number of studies have implied a significant role for ID1 and ID3 in breast cancer progression and metastasis." (PMID 32766238, 2020). "Another interesting observation derives from glioma and breast cancer, where the treatment with CBD or the CB2 agonist O-1663 exerts the inhibitory effect on cancer cell invasion through a down-regulation of Id-1 and Sox-2 protein expression." (PMID 31979368, 2020). "In advanced stages of breast cancer, CBD (1.5 μmol/L) reduced metastasis through down-regulation of the transcriptional regulator Id1, which plays a critical role in mediating breast cancer tumorigenicity." (PMID 31979368, 2020). "TGF-β-ID1 signaling inhibits Twist1 and promotes metastatic colonization via MET in breast cancer, whereas ID1 induces MET in metastatic cells during lung colonization." (PMID 33170151, 2020). "In a mouse model of advanced breast cancer with lung metastases, CBD reduced the degree of metastasis by downregulating ID-1." (PMID 30987191, 2019). "Targeting ID1 and ID3 by a specific peptide aptamer induces E-box promoter activity, cell cycle arrest and apoptosis in breast cancer cells." (PMID 30899759, 2019). "Other investigators demonstrated that Id-1 induced angiogenesis through HIF-1α-mediated VEGF activation in human endothelial cells, breast cancer, and hepatocellular carcinoma." (PMID 31640815, 2019). "It is well known that Id1 is induced by BMP signaling, but TGFβ can also induce Id1 in human breast cancer cells." (PMID 30463358, 2018). "A peptide aptamer (Id1/Id3-PA7) has been developed, which induces cell cycle arrest and apoptosis in ovarian and breast cancer cells by inhibition of Id1 and Id3." (PMID 28122577, 2017). "Regarding breast cancer specifically, one study has reported that BMP-2 promotes breast tumour related angiogenesis through stimulating p38 MAPK pathway and ID-1 expression." (PMID 28733469, 2017). "Id1 also increases breast cancer stem cell (CSC) population and activity in human breast cancer lines." (PMID 25938540, 2015).